CSP1 (CS pseudogene 1)
Gene: Processed pseudogene on chromosome 2 (63,717,122 to 63,717,899, forward strand). Ensembl gene ENSG00000228872.
Diseases named in the same sentence as CSP1 in open-access papers:
CSP1 is named in the same sentence as 18 diseases in open-access papers, as found by Europe PMC text mining. Sharing a sentence is not in itself a finding about the gene and the disease. The quoted sentences say what the papers report.
acute pneumonia (2 papers, 2011 to 2025). "In addition, our previous research has also demonstrated that the exogenous provision of CSP1 has limited effect on the development of natural competence during pneumonia-derived sepsis." (PMID 39935640, 2025). "We examined whether CSP1-E1A could attenuate the virulence of S. pneumoniae D39 using mouse model of acute pneumonia in two independent experiments." (PMID 21909280, 2011). "Importantly, CSP1-E1A is able to attenuate the expression of competence-regulated pneumococcal virulence factors LytA and CbpD in vitro, and reduced the mortality of mice in a pneumonia model of lung infection by S. pneumoniae." (PMID 21909280, 2011). "Importantly, CSP1-E1A was able to attenuate the virulence of S. pneumoniae during lung infection in mice, as well as inhibiting the ability of pneumococcus to acquire both an antibiotic resistance gene and a capsule gene during mouse models of acute pneumonia and bacteremia infections." (PMID 21909280, 2011). "Two of these analogues, CSP1-E1A and CSP2-E1A, competitively inhibit the ability of S. pneumoniae to acquire the streptomycin resistance rpsL gene and the capsule gene cap3A during mouse models of acute pneumonia and bacteremia." (PMID 21909280, 2011).
Sepsis (2 papers, 2025). Sepsis is defined as life-threatening organ dysfunction caused by a dysregulated host response to infection. "In this study, we compared the expression profiles of six early, late, and delayed com genes during the in vitro CSP1-induced competent state versus the naturally developed competent state during pneumonic sepsis." (PMID 39935640, 2025). "Expression of cleaved CSP-1 increased by ~ 5-fold (p < 0.0001) in the WT Sepsis group compared with the WT Sham group." (PMID 41315622, 2025). "Activation of caspase 1 (CSP-1) by the NLRP3 inflammasome during sepsis leads to pyroptosis and massive release of high-mobility group box protein (HMGB1), which is one of the lethal mechanisms of sepsis." (PMID 41315622, 2025). "In the Ager−/− Sepsis group, cleavage CSP-1 was not different from the Ager−/− Sham group." (PMID 41315622, 2025). "Thus, the absence of Csp-1-mediated inflammation in Ager−/− mice may indicate a potential improvement in muscle function after sepsis." (PMID 41315622, 2025).
allergic contact dermatitis (1 paper, 2026). An inflammatory skin condition caused by an immune response to direct contact between the skin and an allergen. "Activation of MrgprB2 by competence-stimulating peptide-1 (CSP-1), a QSM produced by Gram-positive bacteria, has recently been shown to promote antibacterial immunity, whereas its activation by PAMP-12 has been implicated in allergic contact dermatitis (ACD) and itch." (PMID 41924265, 2026).
bacteremia (1 paper, 2011). "In contrast, inhibition of competence regulon by systemic delivery of CSP1-E1A in an IV model of bacteremia should be avoided until further clarification." (PMID 21909280, 2011). "Based on this finding, one can surmise that administration of CSP1-E1A may have the unintended consequence of exacerbating virulence in IV model of mouse bacteremia." (PMID 21909280, 2011).
diabetes (1 paper, 2022). "CSP1 was increased in the saliva of patients with periodontitis, pancreatic cancer, and diabetes implying its involvement in both oral and systemic diseases." (PMID 35613108, 2022).
pneumococcal infection (1 paper, 2011). Infections with bacteria of the species streptococcus pneumoniae. "The ability of CSP1-E1A to inhibit the expression of LytA and CbpD in vitro reveals the possibility of using this peptide analogue to attenuate pneumococcal infection." (PMID 21909280, 2011).
tauopathy (1 paper, 2024). Neurodegenerative disorders involving deposition of abnormal tau protein isoforms (tau proteins) in neurons and glial cells in the brain. "The consequence of caspase activity loss of function in xbp-1s-mediated tauopathy suppression was analyzed using a C. elegans mutant strain [csp-1 (ok2570); referred to as csp-1 (−/−)]." (PMID 39060347, 2024). "Because xbp-1s-mediated tauopathy behavioral suppression requires csp-1, we also measured csp-1 loss of function effects on total tau protein by immunoblot." (PMID 39060347, 2024). "Taken together, five genes identified as responsive to XBP-1s in the transcriptomic data with a previously known association with ATF6n (csp-1, dnj-28, hsp-4, ckb-2, and lipl-3) are all essential for xbp-1s-mediated tauopathy suppression in C. elegans." (PMID 39060347, 2024). "Tau (high); xbp-1s animals were crossed with csp-1 (−/−) animals to understand the effect on tauopathy phenotypes." (PMID 39060347, 2024). "From this analysis, we nominated multiple genetic modifiers of tauopathy associated with XBP-1s/ATF6 in C. elegans, including csp-1, dnj-28, hsp-4, ckb-2, and lipl-3." (PMID 39060347, 2024). "To test whether the involvement of csp-1 in xbp-1s-mediated tauopathy suppression is broadly applicable to overall caspase function, we crossed ced-3 (−/−) animals [ced-3 (n1286)] with Tau (high); xbp-1s animals." (PMID 39060347, 2024). "Taken together, these data demonstrate overall caspase activity via either CSP-1 or CED-3 is necessary for xbp-1s gain of function to suppress behavioral and biochemical tauopathy phenotypes observed in the C. elegans Tau (high) background." (PMID 39060347, 2024).
urea cycle disorder (1 paper, 2023). A genetic inborn error of metabolism characterized by the deficiency of one of the enzymes necessary for the urea cycle. "In the case of valproate, pharmacogenetic testing is helpful for certain genes, i.e., POLG, OTC, and CSP1, when a mitochondrial disorder or a urea cycle disorder is suspected." (PMID 36873203, 2023).
infection (5 papers, 2011 to 2024). The state of being infected such as from the introduction of a foreign agent such as serum, vaccine, antigenic substance or organism. "The vast majority of Cs11 cells were eradicated by CSP1 within 10 hours of infection at MOIs greater than 0.001." (PMID 38572320, 2024). "Among the 21 sensitive strains, CSP1’s infection of the Cs41 strain was peculiar, showing only weak plaques at high phage concentrations in the dilution spot assay." (PMID 38572320, 2024). "It was subsequently infected with CSP1 at various multiplicities of infection (MOI) at 37°C with aerobic orbital shaking." (PMID 38572320, 2024). "Mice lacking this receptor were less effective at clearing bacteria during infection, and activation of Mrgprb2 with exogenous CSP-1 during infection enhanced bacterial clearance." (PMID 37915845, 2023). "Analysis of caspase-7 protein by immunoblot of infected cell lysates definitively revealed cleavage of caspase-7 in csp1−/− BMDM upon infection, and this cleavage was dependent on LLO." (PMID 22807671, 2012). "Inclusion of CSP1-E1A in the infection mix significantly reduced the mortality rate of infected mice from 60% (D39 alone) to 30% (D39 coinoculated with CSP1-E1A)." (PMID 21909280, 2011). "Increasing the CSP1-E1A concentration to 100 μg/mouse in the infection mix significantly reduced the mortality rate of infected mice from 75% (D39 alone) to 40% (D39 coinoculated with CSP1-E1A)." (PMID 21909280, 2011). "We wanted to determine the fate of the two fusion proteins, CSP1-70-mCherry and IBIS1-118-mCherry, that were exported during blood infection, in liver stages." (PMID 34956312, 2021).
tumor (3 papers, 2021 to 2022). "The CSP1 subtype gained a higher microsatellite instability (MSI) score, whereas the CPCS2 subtype obtained a higher cancer-associated fibroblast (CAF) score, stemness-associated score, dysfunction score and tumor immune dysfunction and rejection score (TIDE)." (PMID 36581992, 2022). "In patients, CSP1 is highest in tumors with LKB1 loss and is correlated with poorer patient prognosis in stage I/II LUAD but not in later stages, suggesting a role for CSP1 in tumor initiation and/or progression." (PMID 34944063, 2021).
cancer (2 papers, 2022 to 2023). A tumor composed of atypical neoplastic, often pleomorphic cells that invade other tissues. "While the HCC areas stained positively for CSP1, both biliary lesions in these cancers stained positively, indicating that these lesions express markers of both biliary and hepatocellular cells, implicating transdifferentiation ability in these cells." (PMID 38047594, 2023).
metabolic disease (1 paper, 2021). A congenital disorder (due to inherited enzyme abnormality) or acquired (due to failure of a metabolically important organ) disorder resulting from an abnormal metabolic process. "Compared to the MNR group, amino acid metabolism, nervous system, translation, metabolic diseases were obviously enhanced and transcription, membrane transport was significantly weakened in three CSP-1 treated groups." (PMID 34966769, 2021).
CSP1 also shares sentences with these, for which no sentence is quoted: cleft palate (1 paper); coronary artery disease (1); malaria (1); pancreatic cancer (1); periodontitis (1); type II diabetic (1).